GLI1 (GLI family zinc finger 1)
Diseases named in the same sentence as GLI1 in open-access papers (continued):
Sharing a sentence is not in itself a finding about the gene and the disease.
tumor (continued). "Furthermore, HIF-1α staining intensity was positively correlated with GLI1 expression, an important component of SHH pathway, in NB tumor samples, which suggests HIF-1α as well as SHH signaling may play an important role in NB initiation or progression." (PMID 25811359, 2015). "Studies of Gli-1 in vivo report increased expression in four out of five paired normal and tumor clinical samples, which was not statistically significant, which could be due to small sample size." (PMID 26389956, 2015). "However, while PTCH1 and GLI1 were expressed in all metastatic tumor samples, only 3 out of 12 localized tumor samples and none of the benign tissue samples expressed these genes." (PMID 23880852, 2013). "To further probe the molecular basis for GLI1 activation in SUM149 cells, we tested the effects of a direct GLI inhibitor, GANT58, which has been reported to block GLI1-induced transcription in vitro and prevent additional tumour growth in xenograft tumour models." (PMID 21505458, 2011). "At the endpoint of the experiment, no statistically relevant difference in human (tumor) or mouse (stroma) Ptch1 or Gli1 mRNA levels could be identified in the extracted tumor mRNA (P>0.05)." (PMID 21698280, 2011). "In addition, we found that even in the tumor with elevated expression of hedgehog target genes Gli1 and PTCH1, expression of SHH is not necessarily high, suggesting other mechanisms of hedgehog signaling activation in the cancer." (PMID 19943941, 2009). "Indeed, postoperative adjuvant chemotherapy failed to improve the prognosis of patients with Gli-1 nuclear-positive tumours." (PMID 18475300, 2008). "Their objective was to determine whether or not synthetic miRNA targeting Gli-1 mRNA could be used to inhibit tumor cell proliferation in ovarian SK-OV-3 and pancreatic MiaPaCa-2." (PMID 19440450, 2008). "However, GLI1‐altered neoplasms can be distinguished by the absence of the classic triad." (PMID 39776317, 2025). "Moreover, Gli1, a nuclear transcription factor of the Hh signalling pathway, can directly induce Snail upregulation and decrease the expression of E-cadherin that facilitates epithelial–mesenchymal transition (EMT) in ovarian cancer, thereby promoting tumour metastasis." (PMID 36358596, 2022). "However, the expression of GLI1 was not correlated with tumor stage." (PMID 36046646, 2022). "In addition to retaining all GLI1 functional domains and acting as a terminal effector of the SHH-PTCH1-SMO signaling axis, tGLI1 has gained the ability to activate the expression of at least ten genes leading to tumor growth, angiogenesis, migration, invasion, and stemness." (PMID 36077791, 2022). "Moreover, since BMI1 appears to be a crucial transcription factor regulated by Gli1, having shown that BMI1 inhibitors can control thyroid CSC self-renewal, BMI1 inhibitors should be further evaluated for their inhibitory activity on tumor growth and metastasis." (PMID 33499351, 2021). "Conversely, conditional Rosa26 knock-in allele of GLI3T, which was proven to downregulate GLI1 and GLI2 expression in NIH 3T3 cells, resulted in reduced PANIN lesion formation, reduced proliferative pancreatic cells (absence of Ki67 staining), and delayed PDAC tumor formation." (PMID 34572373, 2021). "However, decreased GLI1 levels do not always correlate with tumor response." (PMID 34572373, 2021). "Indeed, ESFT show deregulated expression of GLI1 and this appears critical for the ESFT phenotype, since genetic or pharmacological inhibition of GLI1 reduces the EWS/FLI1 transformation activity, impairs in vitro cell proliferation and colony formation, and abrogates in vivo tumor growth." (PMID 31244888, 2019). "In addition, the authors found that even in the tumor with elevated expression of the hedgehog target genes Gli1 and PTCH1, expression of Shh is not correlated with Hh target gene expression, suggesting other mechanisms of hedgehog signaling activation in this particular cancer type." (PMID 23303278, 2013).
tumor (continued). "Although both treatments dramatically reduced tumor invasion and reversed EMT progress induced by hypoxia, GLI1 siRNA could not interrupt the hypoxia-mediated increase in SMO; conversely, blocking SMO function by cyclopamine decreased the expression of the transcription factor GLI1." (PMID 23786654, 2013). "Independent of tumor characteristics, such as histology and grades, higher expressions of SHH, PTCH1, PTCH2, and GLI1 have shown beneficial prognostic influence, whereas GLI2, GLI3, and SUFU are correlated with adverse clinical outcomes in OC patients." (PMID 40565349, 2025). "The protein levels of UHRF1, GLI1, CD133, and CD44 displayed similar expression patterns in HCC tumor and paired nontumor tissues, and overexpression (defined as a twofold increase in tumor) of these proteins was observed in nearly 50% of the samples." (PMID 37380646, 2023). "Although the patient declined to undergo further gene detection, tumor cells were SS18-SSX negative and Gli1 positive by immunohistochemical staining." (PMID 38023244, 2023). "In this study, the treatment with LDE225, the SMO inhibitor, showed an inefficient suppression of LMS tumor growth, concomitantly with no changes in SMO and Ki67 protein expression, as well as in gene expression of SMO, GLI1, and GLI2." (PMID 34642915, 2022). "Canonical activation of the pathway via genetic aberrations in pathway components and noncanonical activation of GLI1 and GLI2 transcription factors in tumor cells are oncogenic." (PMID 36010600, 2022). "This GLI1 regulation system independent of the HH-PTCH1-SMO axis indicates the existence of an interface between HH signaling and other pathways during tumor progression." (PMID 33637972, 2021). "To further examine the function of GLI1 in liver CSCs, we detected the expression levels of GLI1 in HCC tumors and peri-tumor tissues, oncespheres and non-sphere cells, as well as liver CSCs and non-CSCs." (PMID 34649567, 2021). "Data from another group supported the tumor cell-intrinsic activation of Hh signaling: when enriching for CD133+ as a marker for cancer stem cells, this study reported increased GLI1 and HHIP expression in CRC cancer stem cells compared to normal mucosa." (PMID 33498528, 2021). "Multivariate analysis demonstrated the dominant role of TGFB, followed by that of GLI1/2, not HH, in predicting mesenchymal/EMT and cell stemness metagene expression in a broad array of tumor types." (PMID 32879407, 2020). "A unique study using arsenic trioxide, a non-specific inhibitor of Gli1/2, in a xenograft mice model demonstrated the rationale of targeting the SHH cascade in order to block ES tumor growth." (PMID 33228057, 2020). "Moreover, although GLI1 suppression is dose- and exposure-dependent, a reduction of GLI1 expression did not always correlate with tumor response in the phase 1 efficacy and safety study for sonidegib, most likely due to limited sample size, indicating resistance may develop despite GLI1 inhibition." (PMID 32973971, 2020). "GLI1 can be activated non-classically by other pathways, such as PI3K-AKT, CXCR4, RAS, and TGF-beta, in tumor cells, independent of SHH1." (PMID 31783569, 2019). "Down-regulation of GLI transcriptional factors (GLI1 or GLI2), but not SMO signaling inhibition, reduces tumor sphere formation, a characteristics of tumor initiating cell (TIC)." (PMID 30382189, 2019). "Consistently, genetic silencing or pharmacological inhibition of GLI1, but not of SMO, reduces LAC tumor growth and stemness in vitro and in vivo." (PMID 31244888, 2019). "And the results indicated that the tumor treated with dioscin had a significant decrease in the expression of β-catenin, but not NICD1 or GLI1, when compared to the Vehicle group." (PMID 29497056, 2018). "In this study, we evaluated the fundamental roles of ASPP2 in tumor progression and the TME via the noncanonical Hh pathway involving aPKC-ι/GLI1 signaling in GBC." (PMID 30389910, 2018).
tumor (continued). "We compared mRNA expression levels of GLI1 in 26 tumor specimens and GEFT in 33 tumor specimens to normal muscle tissues using real time PCR." (PMID 24743780, 2014). "Confocal immunofluorescence images showed that GLI1, one of Hh signaling factors was colocalized with CDO, and additionally its expression was also highly observed in grade-2 and -3 tumor lesions, not in grade-4." (PMID 25369201, 2014). "FOXM1 expression is enhanced by EWS/FLI1, though, unlike other tumor systems, it is not driven by expression of the EWS/FLI1 target GLI1." (PMID 23365673, 2013). "However, our RNA-seq analysis revealed that it was not GLI1 but rather GLI2 and GLI3 that were activated in paclitaxel-resistant NSCLC cells, potentially due to alterations in the tumor microenvironment." (PMID 38228910, 2024). "Interestingly, GLI1, a transcription factor previously thought to be critical for SHH-induced tumourigenesis, was found to be non-essential for tumour formation, as MBs developed even in GLI1 null mutant mice." (PMID 39568072, 2024). "Indeed, despite the fact that hypoxia triggered Hh-mediated tumor stromal interactions and increased sonic secretion, the authors did not observe any effects on SMO and GLI1 expression." (PMID 36230699, 2022). "SOCS1, an IFN-γ/STAT1 inhibitor, is activated by HH signaling pathway itself to create a negative feedback loop and a downstream target of GLI1 and GLI2, which upregulates its transcriptional activity and subsequently relieve the IFN-γ/STAT1 form obstructing tumor growth." (PMID 33494284, 2021). "In LAD tumor-spheres and cell lines, paracrine SHH from LAD epithelia activated the pathway in stroma to express VEGF that in turn, bound to NRP2 receptor to activate the MAPK pathway and express GLI1 in a non-canonical manner." (PMID 32108165, 2020). "Henceforth, changes observed in the behavior of Luminal A cell lines treated with Hh inhibitors did not correlate with suppression of GLI1, PTCH1, and SMO transcripts, thus changes observed in tumor cell behavior are likely the result of off-target effects or non-canonical Hh signaling mechanisms." (PMID 31658643, 2019). "Furthermore, inactivation of SNF5, a tumor suppressor of the SWI/SNF chromatin remodeling complex, leads to constitutive noncanonical activation of GLI1 in malignant rhabdoid tumors." (PMID 30558232, 2018). "To understand whether there are any crosstalks between Gli1 regulating and EMT or not, we first examined the expression of EMT markers (E-cadherin, vimentin) in the tumor tissues by qRT-PCR and divided the patients into low level and high level." (PMID 27863385, 2016). "Interestingly, we observed heterogeneous expression of GLI1 and NANOG also within alveolar RMS patient tumor cores but without prognostic significance (data not shown)." (PMID 26189795, 2016). "Recently, it has been shown that GLI1 expression in PDA is independent of the HH–PTCH–SMO signaling pathway and that it is essential for the proliferative and transformation potential of the tumor cells." (PMID 26633513, 2015). "Additionally, the involvement of GLI1 downstream target genes such as PTCH1, Cyclin D2, Plakoglobin, NKX2.2 and PAX6 have not been studied in either tumor." (PMID 21059263, 2010). "Moreover, consistent with the ability of SIAIS361034 and GDC-0449 against tumor growth, RT-qPCR analysis revealed that SIAIS316034 significantly inhibited the expression of Gli1 mRNA in tumor tissues, while no alteration of the Gli1 mRNA levels was observed in tumors exposed to GDC-0449." (PMID 36438482, 2022).
tumor (continued). "Mechanically, the tumor-suppressive functions of AIM2 in CRC were mediated through its participation in repressing the AKT/mTOR pathway, and the inactivated AKT/mTOR failed to increase Gli1 protein expression, resulting in the inhibition of cell proliferation and migration." (PMID 33291082, 2020).
cancer (529 papers, 2004 to 2026). A tumor composed of atypical neoplastic, often pleomorphic cells that invade other tissues. "Gli1 is a transcriptional effector at the terminal end of the Hedgehog (Hh) signaling pathway whose aberrant activation is associated with a multitude of cancers including PCa." (PMID 39748059, 2025). "For example, LDE225 is the candidate drug against the synthetic lethal target GLI1 (inhibits GLI1 mRNA expression) in cancers deficient in INI1." (PMID 40065228, 2025). "We conducted an immune infiltration analysis of GLI1/2/3, and our results revealed their strongest positive correlation with cancer-associated fibroblasts (CAFs) in tumors, followed by endothelial cells and macrophages." (PMID 38498906, 2024). "This study aimed to unravel the genetic alterations of GLI1/2/3 in cancer and their association with the immune microenvironment and related signaling pathways." (PMID 38498906, 2024). "Other in vivo findings have shown that the BET inhibitor JQ1 also inhibits TGF-β1-dependent gene expression and BRD4 binding at the Gli1 promoter region in cancer-associated fibroblasts (CAFs), reducing fibroproliferation and cancer cell proliferation." (PMID 39215370, 2024). "Glioma-Associated Oncogene Homolog 1 (GLI1), a transcription factor implicated in cancer biology, has shown varying roles in different cancers." (PMID 39483334, 2024). "GSEA analysis identified mechanisms associated with GLI1, GLI2, GLI3, and GLI1/2/3 gene sets in different cancers, where they were primarily linked to EMT activation." (PMID 38498906, 2024). "Overexpression of GLI2 has been reported to cause resistance to targeted cancer therapy in cancer cells, and another study reported that knockdown of GLI1 and GLI2 restored sensitivity to vemurafenib-resistant cells." (PMID 36875125, 2023). "According to the comparison of GLI1 level in cancer and control samples, higher expression was associated with KIRC samples what is consistent with our results." (PMID 37964226, 2023). "In this context, GLI1-mediated Hedgehog signaling has been implicated in various aspect of OC progression including cancer stemness." (PMID 36977707, 2023). "Glioma-associated oncogene family zinc finger 1 (GLI1) is a transcription factor that mediates cancer cell proliferation." (PMID 35819638, 2022). "Of special interest are the pre-mRNAs encoding AZIN1, BLCAP, SON and GLI1, all of which display dysregulation in various cancer types." (PMID 34882682, 2021). "More interestingly, DYRK1B can enhance a zinger finger protein, glioma associated transcription factor (GLI1), to increase canonical Hedgehog (Hh) signaling, which is essential for cancer development and stemness." (PMID 34830933, 2021). "Increased expression of GLI1 has been shown to be associated with metastasis, increased proliferation, and the enrichment of cancer stem cells." (PMID 34370741, 2021). "Although GLI1 expression has been frequently associated with poor prognosis in many known cancers, SMO inhibitors are ineffective in treating various cancers despite showing antitumor activity in preclinical studies." (PMID 34572373, 2021). "Increased expressions of GLI1 cause activation of Hh signaling, which induce anti-apoptotic and anti-inflammatory effects on cancer cells." (PMID 33489917, 2020). "We have also previously verified that cancer-associated fibroblasts induce EMT through β1 integrin-mediated upregulation of GLI1 in GC." (PMID 33170154, 2020). "Genistein (phase I and II), an isoflavone isolated from Genista tinctoria, has been shown to inhibit Gli1, causing the growth suppression of different tumors and the cancer stem niche." (PMID 32984007, 2020). "The cells were then evaluated for GLI1 expression, along with pluripotency markers associated with populations of cancer stem cells." (PMID 32899449, 2020).
cancer (continued). "Chen et al15 demonstrated that Shh and Gli1 were overexpressed in human GC tissues and were associated with deeper cancer invasion, an increased likelihood of lymph node metastasis, and a poor pTNM stage." (PMID 32328197, 2020). "Aberrant expression of GLI-1 (Glioma associated oncogene homolog 1) is a key culprit in the metastasis, invasion, and proliferation of various cancer cells." (PMID 33489917, 2020). "Glioma-associated oncogene homolog 1 (Gli1), affects the progression and the stemness characteristics of malignant carcinoma." (PMID 32430068, 2020). "SMO, in turn, activates the glioma-associated oncogene (Gli) transcription factors, Gli1 and Gli2 9, and turns on the Shh signaling pathway, which promotes cancer cell proliferation." (PMID 31417657, 2019). "Understanding the combinatorial protein landscape in this locus will be important to interrupting the GLI positive feedback loop and providing new therapeutic approaches to cancers associated with GLI1 overexpression." (PMID 31085420, 2019). "This activation causes the activation of GLI1, a nuclear mediator of the Hedgehog pathway that mediates and regulates various genes important in different stages of cancer development and growth." (PMID 30871059, 2019). "Many Hh-dependent cancers are driven by activating mutations that occur downstream of Smo, affecting the transcription factors known as glioma-associated oncogenes (Gli1–3), which mediate the transcriptional effects of Hh pathway activation." (PMID 31137846, 2019). "Increased expression of GLI1 has been associated with poor prognosis of carcinomas stemming from the oral cavity, the esophagus, the lung, and the skin." (PMID 30978209, 2019). "Earlier, SHH and GLI1 over-expression have been associated with poor prognosis in different types of cancers including breast, colon, glioma and prostate." (PMID 29329585, 2018). "Within this family of transcription factors, upregulated GLI1 expression and transcriptional activity is associated with poor patient prognosis in several cancers." (PMID 29930746, 2018). "Previous studies have linked the Hh-Gli1 signaling pathway to numerous human cancers, including CRC." (PMID 28148279, 2017). "In consistent with cancer relapse, we also found that patients with high expression of GLI1/GLI3 and associated molecules in the primary tumors had worse patient survival." (PMID 28413604, 2017). "Together, either IL-6 exposure or continuous lenalidomide treatment enhanced A-to-I editing of GLI1 as well as other cancer-associated associated transcripts, including APOBEC3D, AZIN1, and MDM2." (PMID 29203771, 2017). "GLI1 is an oncogene and its increased expression is associated with many cancers, acting as a marker of HH signaling activation." (PMID 27548161, 2016). "Despite the fact that GLI1 is a highly conserved gene in HH signaling, new mutations have been identified in this gene in different types of cancer." (PMID 26633513, 2015). "In several cancers, Hedgehog (Hh) signalling has been implicated in the regulation of cell survival and proliferation, and Gli1 protein is one of the critical transcription factors that mediate the Hh signalling pathway." (PMID 26218750, 2015). "Apart from cancers, mutations in GLI1 were found in Hirschsprung disease, which is characterized as abnormal neural crest cells differentiation." (PMID 26633513, 2015). "It is also necessary to analyze the roles of the different GLI1 mutations that are found in cancer on the development and progression of the cancer." (PMID 26633513, 2015). "Because of the mutation of components of the Hh signal such as SMO, more downstream events such as the binding of GLI1 on DNA would be affected by the inhibition because of the mutation of components in many cancers." (PMID 24454566, 2014). "The high expression level of GLI1, the key downstream effector of the Hedgehog signaling pathway, is associated with unfavorable overall survival in cancer patients." (PMID 25229616, 2014).